SUCNR1 (succinate receptor 1)
Diseases named in the same sentence as SUCNR1 in open-access papers (continued):
Sharing a sentence is not in itself a finding about the gene and the disease.
inflammatory bowel disease (4 papers, 2020 to 2023). A spectrum of small and large bowel inflammatory diseases of unknown etiology. "Furthermore, succinate levels were found to be elevated and SUCNR1 expression to be increased in tissues from patients with inflammatory bowel disease." (PMID 36977699, 2023). "Succinate levels and SUCNR1-expression were analyzed in intestinal resections from non-Inflammatory Bowel Disease (non-IBD) subjects and CD patients with stenosing-B2 or penetrating-B3 complications and in a murine heterotopic-transplant model of intestinal fibrosis." (PMID 32365557, 2020).
Insulin resistance (4 papers, 2022 to 2025). Increased resistance towards insulin, that is, diminished effectiveness of insulin in reducing blood glucose levels. "The finding is also in agreement with the study reported in a Nature Immunology paper that proposed the view that the WAT inflammation precedes the induction of insulin resistance in the HFD-feeding myeloid SUCNR1 deficiency mice." (PMID 36434066, 2022). "Additionally, SNPs in SUCNR1, a gene encoding succinate receptor 1, have been implicated in placental metabolism and insulin resistance, with increased succinate levels observed in GDM patients." (PMID 40076938, 2025). "Mice with β cell–specific Sucnr1 deficiency exhibited impaired glucose tolerance and insulin secretion on a high-fat diet, indicating that SUCNR1 is essential for preserving insulin secretion in diet-induced insulin resistance." (PMID 38713514, 2024).
type 2 diabetes (4 papers, 2017 to 2024). "Here the authors show high succinate levels in mice with type 2 diabetes and that succinate can signal through succinate receptor 1 on osteoclasts to induce bone resorption." (PMID 28561074, 2017). "We therefore investigated whether succinate receptor 1 (SUCNR1) could play a role in the development of adipose tissue inflammation and type 2 diabetes." (PMID 28382382, 2017).
colorectal cancer (3 papers, 2016 to 2024). A primary or metastatic malignant neoplasm that affects the colon or rectum. "The SUCNR1 functions as a receptor for the citric acid cycle intermediate succinate, involved in the renin-angiotensin system and from its function less likely to be associated with a colorectal cancer risk." (PMID 26872740, 2016).
liver diseases (3 papers, 2017 to 2023). "This indicates that like its control of inflammation more broadly, the potential of SUCNR1 in treating metabolic and inflammatory mediated liver disease is complex." (PMID 37484963, 2023). "Meanwhile, SUCNR1 antagonists have been studied in many fields, such as Advinus Therapeutics which is working on SUCNR1 antagonists for eye and liver diseases." (PMID 31949465, 2019). "This raises interesting questions about the potential use of SUCNR1 in treating liver diseases like NASH, given that, like many other receptors that inhibit lipolysis in adipose including both FFA4 and HCA2/3, SUCNR1 actions in adipose have protective effects on liver lipotoxicity." (PMID 37484963, 2023).
lung fibrosis (3 papers, 2023 to 2025). "In further in vitro experiments we used IPF patient-derived fibroblasts to examine the contribution of the succinate-SUCNR1 axis towards the expression of important markers of pulmonary fibrosis such as αSMA and collagen." (PMID 40146935, 2025). "In our study, we aim to evaluate the role of succinate and its receptor-succinate receptor 1 (SUCNR1) in the pathogenesis of lung fibrosis, with a focus on fibroblasts, a central cell in IPF." (PMID 40146935, 2025). "A recent study by He and colleagues further corroborate the role of the succinate/SUCNR1 axis in promoting lung fibrosis." (PMID 40146935, 2025). "This presents the need to better understand the role of macrophages and ATII cells with regards to the succinate/SUCNR1 axis in pulmonary fibrosis." (PMID 40146935, 2025). "This calls for further investigation to unravel the potential of SUCNR1 as a therapeutic target for pulmonary fibrosis." (PMID 40146935, 2025). "Thus, both the studies clarify the role of the succinate/SUCNR1 axis in enhancing pulmonary fibrosis." (PMID 40146935, 2025). "Additionally, we sought to assess SUCNR1 expression in murine lung tissue as a consequence of lung fibrosis in the bleomycin murine model of pulmonary fibrosis." (PMID 40146935, 2025). "Thus, our study highlights the role of the succinate-SUCNR1 axis in pulmonary fibrosis." (PMID 40146935, 2025).
periodontitis (3 papers, 2023 to 2025). An acute or chronic inflammatory process that affects the tissues that surround and support the teeth. "Gene knockout or pharmacological antagonism of SUCNR1 counteracts periodontitis-induced bone mass loss, whereas intraperitoneal injection of succinate exacerbates periodontitis-mediated bone microstructure destruction." (PMID 38671918, 2024). "In another study, a small-compound gel formulation was developed that specifically blocks SUCNR1 to prevent and treat periodontitis by inhibiting dysbiosis, inflammation, and bone loss." (PMID 37110157, 2023). "In the periodontal milieu, succinate supplement activates SUCNR1 to exacerbate experimental periodontitis via exaggerated periodontal inflammatory responses." (PMID 40383843, 2025). "Succinate enhances the inflammatory response by activating succinate receptor 1 (SUCNR1) in an experimental periodontitis model." (PMID 38671918, 2024). "Succinate aggravates periodontitis through the succinate receptor, SUCNR1." (PMID 37110157, 2023).
steatosis (3 papers, 2017 to 2024). Increased lipid within the cytoplasm of cells. "The livers of HFD WT and Sucnr1−/− animals showed similar levels of steatosis, reflected by hepatic triacylglycerol levels and H&E staining." (PMID 28382382, 2017). "In fact, in the context of NAFLD, while SUCNR1 antagonists may reduce fibrosis, they could also worsen steatosis." (PMID 38182909, 2024).
age-related macular degeneration (2 papers, 2017 to 2023). Age-related loss of vision in the central portion of the retina (macula), secondary to retinal degeneration. "A similar mechanism has been proposed for microglial cell accumulation in age-related macular degeneration, as SUCNR1-deficient microglial cells show impaired migration towards oxidised LDL (and are unresponsive to succinate)." (PMID 28382382, 2017).
colon cancer (2 papers, 2023 to 2025). "Of them, 10 aging-related CpG sites were mapped to 6 genes (i.e., TNF, BICC1, TBX3, SUCNR1, NCF2, DIP2B), and the altered methylation of cg03037030 located in TNF was associated with the risk of CRC, colon cancer, and rectal cancer, with consistent effect direction." (PMID 41197401, 2025). "The interaction of succinate with succinate receptor 1 (SUCNR1), also known as G protein-coupled receptor-91 (GPR91), on the surface of the epithelial colon cancer cells has been reported to activate EMT." (PMID 37239099, 2023).
Crohn disease (2 papers, 2020 to 2022). A gastrointestinal disorder characterized by chronic inflammation involving all layers of the intestinal wall, noncaseating granulomas affecting the intestinal wall and regional lymph nodes, and transmural fibrosis. "Reinforcing this observation, our study showed a higher expression of SUCNR1 and inflammasome activation in colonic resections from UC patients, in line with that previously reported in the ileum of Crohn ́s Disease patients." (PMID 35327334, 2022). "The essential role played by this process in fistula development and the correlation of succinate levels and SUCNR1 expression with the expression of EMT markers in B3-CD patients suggests the implication of the succinate-SUCNR1 pathway in this important complication of Crohn’s disease." (PMID 32365557, 2020). "As succinate and its receptor (SUCNR1) are involved in intestinal inflammation and fibrosis, we investigated their relevance in EMT and Crohn’s disease (CD) fistulas." (PMID 32365557, 2020).
diabetic nephropathy (2 papers, 2020 to 2024). "The role of SUCNR1 activation in common diabetic complications, including diabetic nephropathy, retinopathy, and NAFLD, all of which have a significant impact on patient health, is the focus of ongoing research and the following subsections." (PMID 38182909, 2024). "Despite these insights suggesting that SUCNR1 inhibition may be a possible treatment avenue for diabetic nephropathy, no such interventions have been executed." (PMID 38182909, 2024).
Hepatic steatosis (2 papers, 2018 to 2025). Steatosis is a term used to denote lipid accumulation within hepatocytes. "We propose the first AOP for BPAF-induced hepatic steatosis: BPAF-SUCNR1 binding (MIE) → macrophage succinate release (KE1) → SUCNR1-mediated Akt inhibition/JNK activation (KE2-4) → hepatic lipid accumulation (KE5) → steatosis (AO)." (PMID 41096986, 2025).
pancreatic cancer (2 papers, 2021 to 2024). "In studies on human cancers, the GPCR succinate receptor 1 (SUCNR1/GPR91) inhibited mitochondrial respiration in gastric, lung, and pancreatic cancer cell lines that were addicted to glutamine." (PMID 39000269, 2024). "Moreover, SUCNR1 protein overexpression has been described in renal, urothelial and pancreatic cancers." (PMID 33916314, 2021).
paraganglioma (2 papers, 2021 to 2022). A benign or malignant neoplasm arising from paraganglia located along the sympathetic or parasympathetic nerves. "In pheochromocytomas and paragangliomas, SUCNR1 activation is known to induce tumor proliferation." (PMID 36551549, 2022).
pheochromocytoma (2 papers, 2021 to 2022). "We confirmed elevated SUCNR1 expression in SDHx PPGLs and after SDHB knockout in progenitor cells derived from a human pheochromocytoma (hPheo1)." (PMID 33776908, 2021). "Immunohistochemical staining of human PPGL tissues with different hereditary backgrounds confirmed elevated SUCNR1 protein expression in SDHB PPGLs and SDHD HNPs, compared to VHL pheochromocytomas." (PMID 33776908, 2021).
renal carcinoma (2 papers, 2022 to 2025). A carcinoma arising from the epithelium of the renal parenchyma or the renal pelvis. "Considering the difference in function that SUCNR1 exerts in renal cancer, we questioned whether it has a distinct immune-altering role in RCC subtypes." (PMID 36551549, 2022).
renal cell carcinoma (2 papers, 2021 to 2022). "Nonetheless, little is known about the prognostic relevance of SUCNR1 and its association with tumor immune infiltrates and microbiota in renal cell carcinoma (RCC)." (PMID 36551549, 2022).
Sepsis (2 papers, 2025). Sepsis is defined as life-threatening organ dysfunction caused by a dysregulated host response to infection. "In sepsis and related inflammatory states, succinic acid promotes the chemotaxis and activation of macrophages through succinate receptor 1 (GPR91), exacerbating the inflammatory response." (PMID 41488672, 2025). "Recent studies have shown that succinate may bind to succinate receptor 1 (SUCNR1) and then activate the PI3K/AKT pathway, which plays an important role in the development of sepsis, ulcerative colitis, and acute lung injury; however, whether this pathway is involved in NEC pathogenesis is unclear." (PMID 41476733, 2025).
serous ovarian cancer (2 papers, 2020 to 2021). "Compared to healthy ovarian surface epithelia (OSE), SUCNR1 was upregulated in serous ovarian cancer epithelia (GSE14407)." (PMID 33062639, 2020).
acute myeloid leukemia (1 paper, 2026). Acute myeloid leukemia (AML) is a group of neoplasms arising from precursor cells committed to the myeloid cell-line differentiation. "Here, we show that low SUCNR1 represents a marker for reduced overall and progression-free survival in acute myeloid leukemia (AML) patients." (PMID 41644523, 2026).
allergic contact dermatitis (1 paper, 2018). An inflammatory skin condition caused by an immune response to direct contact between the skin and an allergen. "The authors proposed that the increased severity of allergic contact dermatitis observed in the Sucnr1−/− mice was due to abnormal mast cell development, which leads to mast cell hyperactivation." (PMID 29520272, 2018).
carcinoid (1 paper, 2022). "Moreover, immunohistochemistry of 20 solid tumors including a maximum of 12 patients each, shows positive SUCNR1 staining in 42% of RCC patients compared to 25% in carcinoid and 9% in urothelial cancer patients." (PMID 36551549, 2022).
Chronic colitis (1 paper, 2022). A chronic inflammatory disease of the large intestine (colon, cecum and rectum). "The role of SUCNR1 in the expression of the inflammasome components in vivo was examined in WT and SUCNR1−/− mice after the induction of chronic colitis." (PMID 35327334, 2022). "Indeed, SUCNR1−/− mice exhibited ameliorated chronic colitis and a higher survival, compared with WT mice." (PMID 35327334, 2022).
depression (1 paper, 2025). "Collectively, these genes contribute to diverse regulatory pathways, including neurotransmitter metabolism (Tph2), neurotrophic signaling (BDNF), metabolic regulation (Sucnr1), and ribosomal function (Rps26), supporting their multilayered regulatory roles in the development of depression." (PMID 40656047, 2025).
endometriosis (1 paper, 2024). The growth of functional endometrial tissue in anatomic sites outside the uterine body. "In the context of endometriosis, our findings highlight the importance of succinate-SUCNR1 signaling in macrophage polarization and suggest its role in immune regulation." (PMID 38291428, 2024).
epithelial dysplasia (1 paper, 2021).
geographic atrophy (1 paper, 2013). "Genetic analysis of 925 patients with geographic atrophy and 1199 AMD-free peers revealed an increased risk of developing geographic atrophy associated with intronic variants in the SUCNR1 gene." (PMID 23833031, 2013).
head and neck paraganglioma (1 paper, 2021). A benign or malignant extra-adrenal paraganglioma arising from paraganglia in the head and neck. "Previously, we showed elevated expression of succinate receptor 1 (SUCNR1) in SDHB PPGLs and SDHD head and neck paragangliomas." (PMID 33776908, 2021).
nematode infection (1 paper, 2021). "It was suggested that SUCNR1 may not be required or is redundant for sensing SI nematode infection and our data indicate that SUCNR1 is not involved in tuft cell sensing in the abomasum." (PMID 34880874, 2021).
Nephropathy (1 paper, 2021). A nonspecific term referring to disease or damage of the kidneys. "Whereas succinate–SUCNR1 interplay has been proposed as a molecular mechanism in diabetic neuroretinal angiopathy as well as nephropathy, our data imply a role of this pathway also in placental angiogenesis through VEGF." (PMID 34769478, 2021).
oropharyngeal carcinoma (1 paper, 2025). Carcinoma, predominantly squamous cell, arising from the epithelial cells of the oropharynx. "In the case of patients with oropharyngeal carcinomas, SUCNR1 expression was higher in patients with HPV-positive tumors." (PMID 40141095, 2025).
preeclampsia (1 paper, 2021). Preeclampsia is a hypertensive disorder of pregnancy that is characterized by new-onset hypertension with proteinuria presenting after 20 weeks of gestation, and depending on mild or severe forms may initially present with severe headache, visual disturbances, and hyperreflexia. "Whether the succinate–SUCNR1 axis plays a role in other pregnancy pathologies such as preeclampsia is still to be addressed." (PMID 34769478, 2021).
renal clear cell carcinoma (1 paper, 2021). "GPR91 induction can be also observed in VHL-mutant renal clear cell carcinoma cells, and also in HIF2alpha-overexpressing HepG2 cells, raising the possibility that SUCNR1 itself might be one of the many targets of increased transcription which follows activation of the HIF system." (PMID 34957538, 2021).
small cell lung carcinoma (1 paper, 2022). Small cell lung cancer (SCLC) is a highly aggressive malignant neoplasm, accounting for 10-15% of lung cancer cases, characterized byrapid growth, and early metastasis. "To investigate signaling downstream of succinate-SUCNR1, we studied two PNEC-like small cell lung cancer cell lines, DMS454 and DMS53." (PMID 36108628, 2022).
Stroke (1 paper, 2021). Sudden impairment of blood flow to a part of the brain due to occlusion or rupture of an artery to the brain. "The expression levels of cyt c1, COX2, ATP5A, and SUCNR1 were also significantly elevated by 20% (p < 0.01) compared to the Stroke + Saline group (p < 0.01)." (PMID 33806692, 2021).
Ts (1 paper, 2025). "Administration of succinate exacerbated fibrosis during Ts infection, while deficiency in succinate receptor 1 (Sucnr1) alleviated the condition, highlighting the role of the succinate-Sucnr1 axis in fibrosis development." (PMID 40238740, 2025).